MAP3K4 (mitogen-activated protein kinase kinase kinase 4)
Description:
Component of a protein kinase signal transduction cascade. Activates the CSBP2, P38 and JNK MAPK pathways, but not the ERK pathway. Specifically phosphorylates and activates MAP2K4 and MAP2K6.
Synonyms: MEKK 4; KIAA0213; MAPKKK4; MEKK4; MTK1; PRO0412
Tractability: Small molecule: a high-quality ligand is known; it belongs to a druggable protein family. PROTAC: ubiquitination databases record sites on it; its protein half-life has been measured; a small molecule that binds it is known.
Target class: Enzyme; STE protein kinase STE11 family; Kinase; STE protein kinase group; Protein Kinase
Safety:
Unwanted effects reported when the protein is acted on. In parentheses: how it was acted on, where the effect was seen, and who reports it.
cardiac arrhythmia (cardiovascular system; source: Lamore et al. (2017))
Gene: Protein-coding gene on chromosome 6 (160,991,473 to 161,117,385, forward strand). Ensembl gene ENSG00000085511.
Subcellular location: Cytoplasm, perinuclear region
Subcellular location (Human Protein Atlas): Cytosol
Gene Ontology:
Molecular function: MAP kinase kinase kinase activity; protein binding; ATP binding; protein kinase activity; protein serine kinase activity
Biological process: MAPK cascade; positive regulation of JUN kinase activity; positive regulation of p38MAPK cascade; positive regulation of telomere maintenance; response to UV-C; intracellular signal transduction; p38MAPK cascade
Cellular component: cytoplasm; perinuclear region of cytoplasm
Genetic constraint (gnomAD): Loss-of-function variants: 56 observed, 159.94 expected, observed/expected ratio (o/e) 0.35, 90% interval 0.28 to 0.44. The upper end of that interval is the gene's LOEUF score, 0.44, which puts it in group 1 of 6, group 1 being the genes least tolerant of losing a copy. Missense variants: 1,403 observed, 1,868 expected, observed/expected ratio (o/e) 0.75, 90% interval 0.72 to 0.79. Synonymous variants: 648 observed, 669.77 expected, observed/expected ratio (o/e) 0.97, 90% interval 0.91 to 1.03.
Homologues: Orthologues: chimpanzee MAP3K4 (99% identical), macaque MAP3K4 (98% identical), dog MAP3K4 (93% identical), guinea pig MAP3K4 (92% identical), pig MAP3K4 (92% identical), mouse Map3k4 (88% identical), rat Map3k4 (88% identical), rabbit MAP3K4 (85% identical), tropical clawed frog map3k4 (72% identical), Drosophila melanogaster lic (5% identical), Caenorhabditis elegans sek-5 (5% identical), Caenorhabditis elegans sek-1 (5% identical), and 1 more. Paralogues in human: MAP3K3 (12% identical), MAP3K2 (12% identical), NEK1 (11% identical), MAP2K4 (6% identical), MAP2K5 (6% identical), MAP2K1 (6% identical), MAP2K2 (6% identical), MAP2K7 (6% identical).
Diseases named in the same sentence as MAP3K4 in open-access papers:
MAP3K4 is named in the same sentence as 57 diseases in open-access papers, as found by Europe PMC text mining. Sharing a sentence is not in itself a finding about the gene and the disease. The quoted sentences say what the papers report.
breast carcinoma (11 papers, 2013 to 2025). "Additionally, in breast cancer, overexpression of MAP3K4 has been linked to advanced tumor stage, metastasis, and decreased survival." (PMID 39901302, 2025). "For instance, in breast cancer, hsa-mir-200b-3p has been reported to target MAP3K4, suppressing its expression and inhibiting tumor growth and metastasis." (PMID 39901302, 2025). "In response to HER2/HER3 signaling, MAP3K4 is essential for breast cancer cells to migrate and generate extracellular acidification." (PMID 38568424, 2024). "For example, the TNF and MAP3K4-p38Noxa pathways are substantially activated in cystine-dependent breast cancer cells and tumors, rendering them vulnerable to the necrosis caused by cystine deprivation." (PMID 38568424, 2024). "MAP3K4 can be predictive of preoperative radiotherapeutic responses for locally advanced breast cancer." (PMID 35186006, 2021). "MAP3K4 maintains epithelial-mesenchymal transition in trophoblast stem cells, which potentially contributes to breast cancer." (PMID 35186006, 2021). "Infrequent mutations in CBFB, MAP3K4 and ZNF384 are enriched in Stage I, together with classic breast cancer gene AKT1." (PMID 33087126, 2020). "Previously, we demonstrated that heregulin (HRG) stimulation leads to association of MAP3K4 with activated HER3, extracellular acidification and cell migration in MCF-7 breast cancer cells." (PMID 31346208, 2019). "Additionally, MAP3K4 is required for cell migration and extracellular acidification of breast cancer cells in response to HER2/HER3 signaling." (PMID 31346208, 2019). "We observed that EDA2R, MAP3K4, and WWOX exhibited reduced mRNA expression in 1,085 breast cancer tissues compared with 291 normal breast tissues." (PMID 35186006, 2021).
liver cancer (4 papers, 2015 to 2023). An epithelial or non-epithelial malignant neoplasm that arises from the liver. "Therefore, we speculated that miR-199a-3p could target and negatively regulate MAP3K4, and the upregulation of MAP3K4 might eliminate the inhibitory effect of miR-199a-3p on liver cancer." (PMID 37313461, 2023). "In summary, this study provided preliminary evidence that ATXP might have downregulate the expression of MAP3K4 through the plasma exosome miR-199a-3p to further improve liver function and pathological injury in rats with liver cancer, which ultimately delayed the progression of liver cancer." (PMID 37313461, 2023).
endometriosis (3 papers, 2017 to 2021). The growth of functional endometrial tissue in anatomic sites outside the uterine body. "The MAP3K4 gene, in which we had observed SNP rs144240142 to be associated with Stage A endometriosis, is part of two pathways arising from the ST database: the p38 MAPK pathway and the c-Jun amino-terminal protein kinase (JNK) MAPK pathway." (PMID 28333195, 2017). "The GWAS analysis of Stage A disease resulted in a novel associated variant, rs144240142, in an intronic region of MAP3K4, a gene that was also differentially expressed in endometrium from endometriosis cases and controls in our analysis of an independent data set." (PMID 28333195, 2017). "A genome-wide association study analysis revealed that multiple pathways, new variants in MAP3K4, and several pathways linked to MAPK are associated with endometriosis." (PMID 34220510, 2021). "Interestingly, a 2017 study revealed a relatively strong association of rs144240142, inside the MAP3K4 gene (OR = 1.71), but specifically with the mildest forms of the disease (rAFS I/II), and MAP3K4 was differentially expressed according to the stage of the endometriosis." (PMID 34298916, 2021). "MAP3K4 was also shown to be differentially expressed in eutopic endometrium between Stage A endometriosis cases and controls (P = 3.8 × 10−4), but not with Stage B disease (P = 0.26)." (PMID 28333195, 2017). "Our first ever GWAS analysis for Stage A endometriosis (n = 1686 cases) revealed a novel locus, rs144240142 (P = 6.45 × 10−8, OR 1.71, 95%CI 1.23–2.37), an intronic SNP with MAF of 0.01, imputation info score >0.8, within the MAP3K4 gene." (PMID 28333195, 2017).
endometritis (3 papers, 2024 to 2025). An acute or chronic, usually bacterial infectious process affecting the endometrium. "Gene expression levels were considerably higher in endometritis-affected buffaloes than in resistant ones for the genes A2M, TLR2, IRAK3, CCl2, FCAMR, iNOS, ADAMTS20, KCNT2, MAP3K4, MAPK14, FKBP5, and EPHA4." (PMID 38459095, 2024).
melanoma (3 papers, 2019 to 2022). A malignant, usually aggressive tumor composed of atypical, neoplastic melanocytes. "As for MUTYH and MAP3K4, there is only evidence in literature for treatment of degenerative diseases (MUTYH) and melanoma (MAP3K4)." (PMID 34316711, 2021). "On the other hand, the top downregulated genes formed 4 subgroups and were related to melanogenesis (Wnt5a, Mitf, Pomc, Mc1r, Kit), melanoma (Fgf9, Fgf12, Fgf2), MAPK signaling pathway (Ncam1, Prkcb, Map3k4, Pla2g4a, Mapk14, Mapk11), and aging (Tgfbr1, Il6, Nox4)." (PMID 36555664, 2022).
placental insufficiency (3 papers, 2022 to 2024). Failure of the placenta to deliver an adequate supply of nutrients and oxygen to the fetus. "In TS cells and the placenta, MAP3K4 is essential for the IGF1R/IR and Akt signaling pathways, and MAP3K4 kinase inactivation causes FGR driven by placental insufficiency." (PMID 38568424, 2024). "Based on our results, we propose that MAP3K4 plays a critical role in the IGF1R/IR and Akt signaling pathway in TS cells and placenta, and MAP3K4 KI results in FGR caused by placental insufficiency." (PMID 35921893, 2022).
colorectal cancer (2 papers, 2020 to 2025). A primary or metastatic malignant neoplasm that affects the colon or rectum. "For instance, in colorectal cancer (CRC), up-regulation of MAP3K1, MAP3K4, MAP3K7, and MAP3K8 has been associated with tumor progression, activation of oncogenic signaling pathways, and poor prognosis, similar to findings in GC." (PMID 39901302, 2025). "CBFB and ZNF384 are cancer genes for leukemia; RB1 is a gene for retinoblastoma, sarcoma and small-cell lung cancers and MAP3K4 is a gene for pancreatic, breast and colorectal cancers, as listed on the Cancer Gene Census." (PMID 33087126, 2020).
hepatocellular carcinoma (2 papers, 2022 to 2023). A malignant tumor that arises from hepatocytes. "In hepatocellular carcinoma, an additional mechanism has been described for circMAP3K4, derived from the MAP3K4 gene (Mitogen-Activated Protein Kinase 4)." (PMID 36012237, 2022). "The results showed that MAP3K4 was highly expressed in hepatocellular carcinoma (HCC)." (PMID 37313461, 2023).
breast tumours (1 paper, 2018). "Increased expression of MAP3K4 in breast tumours may confer radioresistance through augmented signalling for RT-induced DNA damage repair through G2 arrest thus aiding survival of irradiated cancer cells." (PMID 30285791, 2018). "Therefore, detecting the levels of MAP3K4 expression in breast tumours, may be useful for the prediction of response to RT for tumour downstaging for breast conserving surgery in LABC." (PMID 30285791, 2018).
cardiac hypertrophy (1 paper, 2020). "Although the phenotypic features of physiological and pathological forms of cardiac hypertrophy are distinct, these results indicate that a transcriptional upregulation of Map3k4 may underscore both processes." (PMID 33102519, 2020).
colon adenoma (1 paper, 2017). An adenoma that arises from the colon.
diabetes (1 paper, 2022). "More importantly, key genes of the respective pathways, such as AKT3, FGF2, FGF7, mitogen-activated protein kinase 4 (MAP3K4), MAP3K5, insulin receptor (INSR), AKT3, and mTOR, were also enriched in the analysis, thus explaining the link between diabetes and BCRL subjects in the present study." (PMID 36232660, 2022).
diabetic cardiomyopathy (1 paper, 2025). Diabetic cardiomyopathy is a disorder of the heart muscle in people with diabetes. "Changes in AS of ATP5C1, DCLK2, and MAP3K4 rewire interactions with a “Hypertrophic cardiomyopathy” pathway, and of CACNA1C, TPM3, and ITGB1 rewire interactions with the “Diabetic cardiomyopathy” pathway." (PMID 40337913, 2025).
ependymoma (1 paper, 2020). A WHO grade II, slow growing tumor of children and young adults, usually located intraventricularly. "Firstly, MAP3K4 was involved in MAPK kinase signal transduction, which was a characteristic signaling pathway for discriminating group A subtype ependymoma." (PMID 32266223, 2020).
gastric cancer (1 paper, 2023). A primary or metastatic malignant neoplasm involving the stomach. "The 5-year survival rate of patients with stages I, II and III gastric cancer and weak MAP3K4 expression was significantly greater than that of those with strong MAP3K4 expression (P =0.0102; P < 0.0001; P < 0.0001, respectively)." (PMID 37497404, 2023). "Twenty-four h after transfection with miR-199a-3p inhibitor, the gastric cancer cell line was harvested for western blotting to assess expression of MAP3K4 (MAP3K4 antibody-n-terminal-AF0818 (Affinity) * 100 μL 1:1000)." (PMID 37497404, 2023). "MiR-199a-3p 7 and MAP3K4 are strongly expressed in gastric cancer samples, and are correlated with the patient's prognosis." (PMID 37497404, 2023). "The degree of expression of MAP3K4 in 436 paraffin-fixed samples of human gastric cancer tissue was assessed by immunohistochemical analysis." (PMID 37497404, 2023). "Two hundred and ten gastric cancer cases had a low expression of miR-199a-3p and MAP3K4 simultaneously." (PMID 37497404, 2023). "Ninety-nine gastric cancer cases had a high expression of miR-199a-3p and MAP3K4 at the same time." (PMID 37497404, 2023). "Immunohistochemistry was used to detect the expression of MAP3K4 in gastric cancer." (PMID 37497404, 2023). "We found that MAP3K4 is strongly expressed in 36.92% (161/436) of gastric cancer samples, the strength of expression being correlated with tumor size, Lauren classification, depth of invasion, lymph node metastasis, lymph node metastasis stage, distant metastasis, TNM stage and prognosis." (PMID 37497404, 2023). "Analysis of independent prognostic factors indicated that MAP3K4 expression, depth of invasion, lymph node metastasis and TNM stage are independent prognostic factors for gastric cancer." (PMID 37497404, 2023). "MAP3K4 was strongly expressed in paracancerous non-neoplastic gastric mucosa and in 36.92% (161/436) of samples of gastric cancer tissue, mainly in the cytoplasm." (PMID 37497404, 2023).
intrahepatic cholangiocarcinoma (1 paper, 2024). A carcinoma that arises from the intrahepatic bile duct epithelium in any site of the intrahepatic biliary tree. "For instance, the putative tumor suppressor MAP3K4 potently controls the EMT process and invasive growth in intrahepatic cholangiocarcinoma (iCC), despite being highly down-regulated and frequently mutated." (PMID 38568424, 2024).
Myotonia (1 paper, 2018). An involuntary and painless delay in the relaxation of skeletal muscle following contraction or electrical stimulation. "In DM1 and DM2 individuals without clinical myotonia, splicing of MBNL2, MBNL1, CLASP1, and MAP3K4 showed changes intermediate between those with myotonia and UA subjects." (PMID 30254196, 2018).
pituitary adenomas (1 paper, 2023). "The expression levels of ANXA2, PMAIP1, SPRY2, C2CD4A, APOD, FGF14 and FKBP10 were significantly upregulated while FNDC5 and MAP3K4 were downregulated in the invasive gonadotrophic pituitary adenomas compared to the non-invasive ones." (PMID 36750863, 2023).
psoriasis (1 paper, 2020). An autoimmune condition characterized by red, well-delineated plaques with silvery scales that are usually on the extensor surfaces and scalp. "Psoriasis-associated plasma miRNAs target MAP kinases; it has been reported that miR-148a-3p targets MAPK1, MAP2K3, MAP3K4, and MAP4K3." (PMID 32411787, 2020).
spina bifida (1 paper, 2022). A congenital neural tube defect in which vertebrae are not fully formed. "Furthermore, MAP3K4 KI embryos in a mixed 129/SvEv/C57BL/6N background display developmental defects, including exencephaly, spina bifida, and male gonadal sex reversal demonstrating that MAP3K4 is critical for normal development." (PMID 35921893, 2022).
spina bifida aperta (1 paper, 2020). "Interestingly, we had one case with anencephaly and thoracic lumbar spina bifida aperta (the neural tube was closed in cervical region), who carried two missense mutations in the MAP3K4 gene involved in MAPK signaling (MAP3K4: NM_005922: c.877G > A: p.D293N and c.2711C > G: p.T904S)." (PMID 32650820, 2020).
uterine corpus endometrial carcinoma (1 paper, 2023). A endometrial carcinoma (disease) that involves the body of uterus. "SNV heatmap indicated that the mutation rate of MAP3K4 was the highest, and uterine corpus endometrial carcinoma (UCEC) had the highest mutation rate." (PMID 36835825, 2023).
cancer (22 papers, 2011 to 2025). A tumor composed of atypical neoplastic, often pleomorphic cells that invade other tissues. "Indeed, MAP3K4 is affected by recurrent loss-of-function mutations in different types of cancers." (PMID 31142279, 2019). "In this review, we evaluated the physiological roles of MAP3K4 and the MAP3Ks family, with a particular emphasis on the complex roles of MAP3K4 and its involvement in the mechanisms of cancer cells." (PMID 38568424, 2024). "A deeper understanding of the MAP3K4 mechanism will give rise to better therapeutic strategies for cancer therapy with higher favorable outcome rates." (PMID 38568424, 2024). "MAP3K4 plays significant roles in cancers, but it doesn’t only depend on itself rather relies heavily on the entire pathways." (PMID 38568424, 2024). "To further explore the role of the gene set (DLAT, IDH3B, and MAP3K4) across diverse cancer types, we analyzed their expression levels and mutant profiles." (PMID 36835825, 2023). "MAP3K4 is a component of the mitogen-activated protein kinase pathway, which plays critical roles in cancer development." (PMID 27279334, 2016). "In addition, over-expression of dominant-negative MEKK4, which is the mouse homologue of MAP3K4, blocked differentiation of carcinoma cells via the JNK MAPK pathway." (PMID 31346208, 2019). "Notably, MAP3K4 functions as both a tumor promotor and suppressor, being activated by a variety of factors and triggering diverse downstream pathways that differently influence cancer progression." (PMID 38568424, 2024). "However, we found that cancer cell-lines with MAP3K4 A1199 deletion hotspot mutations were more resistant to all four examined EGFR inhibitors (Erlotinib, Lapatinib, TKI258 and AZD0530) in comparison to cancer cell-lines without MAP3K4 mutations." (PMID 27356755, 2016). "Among the MAP3K family members, MAP3K1, MAP3K4, and MAP3K5 have garnered considerable attention in the context of GC due to their established roles in cancer biology and signaling pathways relevant to gastric tumorigenesis." (PMID 39901302, 2025). "According to this study, MAP3K4 is downregulated when GATA6-AS is expressed, hindering cancer cells from migrating and invading." (PMID 38568424, 2024). "Examples of cancer related genes in the network included GAS6, MAP3K4, PRKD1, PTPRD, and VEGFA." (PMID 34434222, 2021). "MAP3K4 gene is an important component of the MAPK pathway, plays a crucial role in epithelial to mesenchymal transition, supports the male gonadal determination, and has been tested as a prognostic factor in other cancer types." (PMID 31500094, 2019).